AEBP1 (AE binding protein 1)
Description:
[Isoform 1]: As a positive regulator of collagen fibrillogenesis, it is probably involved in the organization and remodeling of the extracellular matrix. [Isoform 2]: May positively regulate MAP-kinase activity in adipocytes, leading to enhanced adipocyte proliferation and reduced adipocyte differentiation. May also positively regulate NF-kappa-B activity in macrophages by promoting the phosphorylation and subsequent degradation of I-kappa-B-alpha (NFKBIA), leading to enhanced macrophage inflammatory responsiveness. Can act as a transcriptional repressor.
Synonyms: ACLP
Tractability: Antibody: UniProt places it where antibodies can reach, with medium confidence; UniProt predicts a signal peptide or a membrane-spanning region; its Gene Ontology location is reachable by antibodies, with medium confidence. PROTAC: ubiquitination databases record sites on it.
Gene: Protein-coding gene on chromosome 7 (44,104,295 to 44,114,565, forward strand). Ensembl gene ENSG00000106624.
Subcellular location: Secreted (Isoform 1); Cytoplasm (Isoform 2); Nucleus
Subcellular location (Human Protein Atlas): Vesicles; Cytosol; Nucleoplasm; Predicted to be secreted
Gene Ontology:
Molecular function: collagen binding; DNA-binding transcription repressor activity, RNA polymerase II-specific; RNA polymerase II transcription regulatory region sequence-specific DNA binding; extracellular matrix structural constituent; metallocarboxypeptidase activity; zinc ion binding
Biological process: negative regulation of transcription by RNA polymerase II; regulation of collagen fibril organization; peptide metabolic process; protein processing; regulation of DNA-templated transcription; proteolysis
Cellular component: extracellular exosome; extracellular matrix; extracellular region; cytoplasm; non-collagenous component of interstitial matrix; nucleus
Genetic constraint (gnomAD): Loss-of-function variants: 69 observed, 114.72 expected, observed/expected ratio (o/e) 0.6, 90% interval 0.49 to 0.74. The upper end of that interval is the gene's LOEUF score, 0.74, which puts it in group 3 of 6, group 1 being the genes least tolerant of losing a copy. Missense variants: 1,444 observed, 1,587.2 expected, observed/expected ratio (o/e) 0.91, 90% interval 0.87 to 0.95. Synonymous variants: 627 observed, 632.64 expected, observed/expected ratio (o/e) 0.99, 90% interval 0.93 to 1.06.
Homologues: Orthologues: chimpanzee AEBP1 (99% identical), chimpanzee AEBP1 (88% identical), pig AEBP1 (87% identical), dog AEBP1 (86% identical), rat Aebp1 (83% identical), mouse Aebp1 (83% identical), guinea pig AEBP1 (81% identical), rabbit AEBP1 (80% identical), tropical clawed frog aebp1 (59% identical), zebrafish aebp1a (42% identical), zebrafish aebp1b (39% identical). Paralogues in human: CPXM2 (35% identical), CPXM1 (30% identical), CPD (20% identical), CPZ (18% identical), CPN1 (17% identical), CPE (16% identical), CPM (11% identical).
Diseases named in the same sentence as AEBP1 in open-access papers:
AEBP1 is named in the same sentence as 90 diseases in open-access papers, as found by Europe PMC text mining. Sharing a sentence is not in itself a finding about the gene and the disease. The quoted sentences say what the papers report.
glioma (21 papers, 2017 to 2026). A benign or malignant brain and spinal cord tumor that arises from glial cells (astrocytes, oligodendrocytes, ependymal cells). "CCK-8 assay revealed that AEBP1 silencing caused a significant decrease in the proliferation of the glioma cell lines." (PMID 32565808, 2020). "AEBP1 has been reported to enhance glioma cell survival, while silencing AEBP1 causes caspase-dependent death of GBM cells; therefore, AEBP1 is a potential oncogenic driver in glioma." (PMID 33224311, 2020). "Confocal immunofluorescent analysis using MitoTracker Red CMXRos, which is used to examine MOMP integrity, revealed a time-dependent loss of MOMP in AEBP1-depleted glioma cells." (PMID 32565808, 2020). "AEBP1 overexpression in glioma is associated with higher tumor grade and worse prognosis." (PMID 32938364, 2020). "Recent studies have shown that AEBP1 plays an oncogenic role in cancer cells of various origins, including glioma, melanoma, gastric cancer, and CRC cells." (PMID 37686580, 2023). "ACT001 was reported to play a critical role in gliomas by targeting gliomas stem cells through inhibition of AEBP1/PI3K/AKT signaling." (PMID 36990974, 2023). "In gliomas, AEBP1 was defined as a potential oncogenic driver, with potential implications for therapeutic intervention." (PMID 36523769, 2022). "They found that AEBP1 expression is increased in human glioma cell lines and that AEBP1 knockdown reduces the expression of NF-κB." (PMID 35559019, 2022). "Because of the heterogeneity between different grades of glioma, we analyzed the prognostic value of AEBP1 in GBM patients additionally." (PMID 34373835, 2021). "The results showed that glioma patients with higher AEBP1 expression have a shorter overall survival (OS) time." (PMID 34373835, 2021). "Next, we determined the relationship of AEBP1 expression and glioma patient survival using the RAMBRANDT and the Cancer Genome Atlas (TCGA) datasets." (PMID 33391492, 2021). "The survival analysis showed that the overexpressed level of AEBP1 was correlated with short survival time in both glioma and GBM patients." (PMID 34373835, 2021). "Given that AEBP1 is important for various cancers 16, 17, including glioma 18, we further investigated if it is a target of ACT001 in GSCs." (PMID 33391492, 2021). "ACT001 inhibited GSC proliferation and glioma sphere formation through targeting AEBP1/PI3K/AKT signaling and prolonged the survival of animals as a single agent or in combination with SHP099 in an orthotopic GSC xenograft." (PMID 33391492, 2021). "Further analysis was performed in TCGA and CGGA datasets, and the results showed that AEBP1 expression in GBM patients was significantly higher than that in lower-grade glioma patients." (PMID 34373835, 2021). "In gliomas, AEBP1 up-regulated PI3KCB transcription, leading to enhanced AKT phosphorylation and cell proliferation." (PMID 33391492, 2021). "Our study further confirms the importance and potential therapeutic intervention implications of CLCF1 and AEBP1 in PTEN mutant glioma." (PMID 34336645, 2021). "AEBP1 is able to act on glioma stem-like cells (GSCs) mediated by PI3K/AKT signaling, which is involved in the initiation and maintenance of tumor cells." (PMID 34938806, 2021). "This water-soluble compound (dimethylaminomicheliolide) exhibits a higher plasma stability than parthenolide and was found to target glioma stem-like cells through regulation of the protein AEBP1 (adipocyte enhancer binding protein 1)." (PMID 34680439, 2021). "We then assessed the expression levels of AEBP1 in normal brain tissues and clinical specimens of glioma patients." (PMID 33391492, 2021). "It was also found that AEBP1 expression was overexpressed in IDH wild type glioma patients and MGMT promoter unmethylation-type glioma patients." (PMID 34373835, 2021).
glioma (continued). "Kaplan-Meier survival analysis revealed a statistically significant worse prognosis for glioma patients with high AEBP1 (> median level) compared to those with low levels of AEBP1 (< median level) in the RAMBRANDT dataset." (PMID 33391492, 2021). "As a result, it was shown that the higher AEBP1 expression was enriched in IDH wild type glioma, which indicated the possibility of AEBP1 to be used as a predictive factor." (PMID 34373835, 2021). "The relation between MGMT promoter methylation and AEBP1 expression was also analyzed, and the result showed that the expression of AEBP1 was higher in MGMT promoter unmethylated glioma patients." (PMID 34373835, 2021). "The expression of CLCF1, AEBP1, and OS9 is significantly associated with the prognosis of PTEN-wt glioma, indeed which are significantly different between high-risk score patients and low-risk patients in the PTEN-mut subgroup (p < 0.001)." (PMID 34336645, 2021). "Collectively, these results demonstrate that cell death in PTEN-proficient glioma cells occurs in a caspase- and Akt-dependent mechanism upon AEBP1 silencing." (PMID 32565808, 2020). "In line with the study conducted by Reddy and colleagues, which examined the effects of AEBP1 overexpression in GBM multiform tumors, Ladha and colleagues sought to analyze the biological significance of AEBP1 overexpression in glioma cells." (PMID 32565808, 2020). "We reveal that AEBP1 exerts its tumor-promoting effects by mainly activating mTOR pathway in Glioma." (PMID 32938364, 2020). "Other experiments were aimed at investigating the involvement of the parthanatos pathway, a PARP-1-dependent cell death mechanism, in AEBP1-depleted U138MG glioma cells." (PMID 32565808, 2020). "Since PI3KCB plays an important role in maintaining genomic integrity, Sinha and colleagues suggest that the decrease in PI3KCB leads to an increase in double-strand breaks in the nuclei of AEBP1-depleted glioma cells." (PMID 32565808, 2020). "The study also demonstrated that the presence of AEBP1 is essential for the survival of glioma cells." (PMID 32565808, 2020). "Through overexpression or knockdown of AEBP1 gene in glioma cell line LN229 and RPPA analysis, we can show that a panel of proteins are significantly affected by the manipulation of AEBP1 expression." (PMID 32938364, 2020). "Since AEBP1 silencing in U138MG glioma cells was shown to lead to cell death, a recent study sought to explore the mechanism by which cell death is induced upon depletion of AEBP1." (PMID 32565808, 2020). "And last, we analyze the relationship between AEBP1 and key proteins to identify that AEBP1 exerts its tumor-promoting effects by mainly activating mTOR pathway in Glioma." (PMID 32938364, 2020). "Overall, these results show that PTEN status determines the choice of cell death pathway in AEBP1 depleted glioma cells." (PMID 31601918, 2019). "For this purpose, AEBP1 was silenced in U138MG glioma cells using 100 nM AEBP1 siRNA pool, which was replenished every 36 hours over a period of 9 days and assessed for cellular viability MTT (3-(4,5-Dimethylthiazol-2-yl)-2,5-Diphenyltetrazolium Bromide)assay." (PMID 31601918, 2019). "We have reconfirmed that PI3KCB is indeed down regulated under AEBP1 down regulated conditions at mRNA and protein level in glioma cells." (PMID 31601918, 2019). "With this background, we were interested to identify the detailed molecular mechanism of cell death in glioma cells under AEBP1 depleted conditions." (PMID 31601918, 2019). "On probing the role of AEBP1 over expression in glioblastoma, we found that both cellular proliferation and survival were affected upon AEBP1 silencing in glioma cells, resulting in cell death." (PMID 31601918, 2019). "Collectively, our findings define AEBP1 as a potential oncogenic driver in glioma, with potential implications for therapeutic intervention." (PMID 31601918, 2019).
glioma (continued). "The present study has also shown that the process of cell death initiation in U138MG glioma cells under AEBP1 depleted condition is possibly mediated through the transcriptional control of PI3KCB." (PMID 31601918, 2019). "In the present study, we deciphered that AEBP1 depletion-induced cell death mechanism in glioma cells and its dependence on the genetic background of tumor cells." (PMID 31601918, 2019). "Together, these data show that AEBP1 down regulation induces caspase-dependent cell death in PTEN-proficient glioma cells." (PMID 31601918, 2019). "AEBP1, for instance, has been implicated in promoting GBM progression through the activation of the NF‐κB pathway, with documented associations with enhanced cellular proliferation and survival in glioma cells." (PMID 40052358, 2025). "For example, the expression value of AEBP1 is higher in the glioma cells, and inhibition of AEBP1 could induce apoptosis of GBM cell lines." (PMID 35783254, 2022). "So we focused on AEBP1 to research for its molecular and clinical characterization in glioma." (PMID 34373835, 2021). "Our study showed that AEBP1 might be an oncogene and a new effective therapeutic target for the treatment of glioma." (PMID 34373835, 2021). "Here, we investigated whether AEBP1 is a new target of ACT001 in gliomas with activating AKT signaling." (PMID 33391492, 2021). "The positive-related genes with AEBP1 were also enriched in positive regulation of cell proliferation, angiogenesis, response to hypoxia, and cell adhesion which related with the malignant progression of glioma." (PMID 34373835, 2021). "The study also points to AEBP1 as a new effective therapeutic target for the treatment of glioma." (PMID 34373835, 2021). "In addition to this, the silencing of LINC00511 expression suppressed cell viability, proliferation, migration, and invasion, and accelerated the apoptosis of glioma cells via a suggested miR-15a-5p/AEBP1 axis." (PMID 34771513, 2021). "AEBP1 was overexpressed in MGMT promoter unmethylation type glioma which might be an important factor in predicting TMZ sensitivity." (PMID 34373835, 2021). "All the results showed above indicated that AEBP1 might play an important role in the malignant progression and chemoresistance in glioma." (PMID 34373835, 2021). "Moreover, it is suggested that Bax and caspase-3 induce early apoptosis in glioma cells, as AEBP1 silencing resulted in the increased expression of these proteins." (PMID 32565808, 2020). "Thus, Cheng and colleagues investigated the effects of AEBP1 silencing in the glioma cell lines, U87MG and U251MG, by transfecting the cells with siAEBP1." (PMID 32565808, 2020). "Finally, we identify that AEBP1 exerts its tumor-promoting effects by mainly activating mTOR pathway in Glioma." (PMID 32938364, 2020). "Since PI3Ks are a family of enzymes involved in the activation of signaling pathways responsible for cell proliferation, growth, and survival, AEBP1-mediated positive regulation of PI3KCB may be one factor that leads to the progression of glioma." (PMID 32565808, 2020). "Additionally, PI3KCB overexpression in AEBP1-depleted glioma cells inhibited the accumulation of γH2AX foci." (PMID 32565808, 2020). "Interestingly, apoptosis was upregulated upon AEBP1 silencing in a time-dependent manner in both glioma cell lines." (PMID 32565808, 2020). "Interestingly, Sinha and colleagues reported that cell death occurs in PTEN-proficient glioma cell line (LN18) upon AEBP1 silencing." (PMID 32565808, 2020). "The fact that AEBP1 is necessary for cellular viability in both PTEN-proficient and PTEN-deficient tumor cells, suggests that AEBP1 can be a good potential target for therapeutic intervention in glioma patients in general irrespective of the PTEN status." (PMID 31601918, 2019).
glioma (continued). "In an initial effort to understand the role of AEBP1 in primary glioma, we performed global gene expression profiling in AEBP1 down regulated U87MG glioma cell line and identified a large number of perturbed genes belonging to categories of cell cycle, differentiation, proliferation and apoptosis." (PMID 31601918, 2019). "Moreover, previous research identified several genomic targets of AEBP1 playing vital roles in the survival of glioma cells." (PMID 28198665, 2017). "The relevant targeted therapy might be effective in glioma patients with AEBP1 overexpression." (PMID 34373835, 2021). "Therefore, it was inferred that the antibody of AEBP1 might be a new select for effective treatment in glioma patients." (PMID 34373835, 2021). "Thus, it would prove useful to investigate whether the mechanism by which cell death occurs due to AEBP1 silencing differs between PTEN-deficient (U138MG) and PTEN-proficient (LN18) glioma cells." (PMID 32565808, 2020). "Thus, targeting AEBP1 could be a promising therapeutic intervention towards the treatment of gliomas, paving the way for more innovative and revolutionary cancer therapy." (PMID 32565808, 2020). "The IHC findings confirmed the increased expression of AEBP1, DCTD, DEPP1, DUSP6, FKBP9, and UGCG with the up‐regulation of glioma grades." (PMID 40052358, 2025). "The expression values of AEBP1, F3, FLNC, IGFBP2, and LDHA were compared among normal brain tissue, low-grade gliomas (LGG), and GBM." (PMID 35783254, 2022). "Due to the higher malignancy of the PTEN-mut gliomas, we explored the independent prognostic signatures (CLCF1, AEBP1, and OS9) for a potential therapeutic target in PTEN-mut glioma." (PMID 34336645, 2021). "In the present study, we discovered that the mRNA expression of AE binding protein 1 (AEBP1) was overexpressed in TMZ chemoresistance cell lines and glioma stem cell lines." (PMID 34373835, 2021). "Due to the higher malignancy of the PTEN-mut glioma, we look for potential therapies targeting the prognostic signatures (CLCF1, AEBP1, and OS9) in this subgroup." (PMID 34336645, 2021). "By analyzing the COSMIC and GSE23806 datasets, we found that the mRNA expression level of AEBP1 was upregulated in TMZ-resistant cell lines and glioma stem cell lines." (PMID 34373835, 2021). "ACT001 inhibits glioma cell proliferation by inhibiting PI3K/AKT activation 14 and AEBP1 activates PI3K/AKT signaling through upregulation of PI3KCB transcription." (PMID 33391492, 2021). "Compared to low grade gliomas (Grade II and III), the expression levels of AEBP1 mRNA was markedly upregulated in GBM." (PMID 33391492, 2021). "The newly elucidated roles of AEBP1 in GSC proliferation and glioma sphere formation provide a strong rationale for targeting this molecule in clinical treatment of human gliomas." (PMID 33391492, 2021). "Kaplan-Meier survival analysis of the TCGA low-grade glioma (TCGA-LGG) and TCGA GBM RNA-Seq datasets further indicated that AEBP1 is a prognostic factor for glioma patients." (PMID 33391492, 2021). "Taken together, this study identifies AEBP1 as a new target of ACT001 and a putative prognostic factor in glioma." (PMID 33391492, 2021). "Compared with the control, TGF-β treatment in GSC 1123 and R39 cells induced AEBP1 expression, activated p-AKT, and promoted cell proliferation and glioma sphere formation." (PMID 33391492, 2021). "The expression level of AEBP1 during different grades of glioma was analyzed in two datasets, and the results showed that it was higher in GBM patients than that in lower-grade glioma patients." (PMID 34373835, 2021). "ACT001 treatment significantly attenuated TGF-β-induced AEBP1 expression, p-AKT, cell proliferation, and glioma sphere formation." (PMID 33391492, 2021). "A glioma cell line LN229 was used to identify major protein players and molecular pathways through RPPA analysis after AEBP1 overexpression and AEBP1 knockdown." (PMID 32938364, 2020).